IL6 (interleukin 6)
Diseases named in the same sentence as IL6 in open-access papers (continued):
Sharing a sentence is not in itself a finding about the gene and the disease.
schizophrenia (continued). "Alterations in neuroinflammatory processes have been suggested to contribute to the development of Schizophrenia (SZ); one component of the inflammatory system that has been linked to this disorder is interleukin-6 (IL-6)." (PMID 31341681, 2019). "In rodent models of MIA, maternal IL-6 released in response to MIA is necessary for schizophrenia-like symptoms in the mouse model and administration of IL-6 alone to pregnant rats is sufficient to cause behavioral changes in the offspring." (PMID 30225350, 2018). "IL-6 gene expression in blood leukocytes, for example, was associated with decreased hippocampal volume in patients with schizophrenia." (PMID 29803226, 2018). "Entrance of pro-inflammatory cytokines; tumor necrosis factor-alpha (TNF-α), interleukin-6 (IL-6) has been shown to be associated with the progression of Parkinson’s disease, Alzheimer’s disease, and schizophrenia." (PMID 29937710, 2018). "The estimated proportion of the effect of inhibiting IL-6 classic signaling on schizophrenia risk that is mediated by CRP (using the IVW estimate from the liberal CRP set as the effect estimate of CRP on schizophrenia risk) was 43.8% (95% CI, 3.3% to 84.2%)." (PMID 29094161, 2017). "Recent meta-analyses of case control studies investigating cytokine genes, indicates polymorphisms in IL-1β, IL-6, and soluble IL-6 receptors (sIL6R) are also associated with risk for schizophrenia." (PMID 28396623, 2017). "IL-6-174G/C polymorphism showed to be associated with increased IL-6 plasma levels and represent a risk factor for schizophrenia." (PMID 29163240, 2017). "Interpreting the magnitude of estimates for the effect of CRP and IL-6 on schizophrenia risk, as well as for the mediated effect of IL-6 by circulating CRP, requires caution." (PMID 29094161, 2017). "It was previously suggested that treatment resistance in schizophrenia is associated with IL-6 elevated levels." (PMID 29163240, 2017). "Our findings support the notion that lower CRP levels and blockade of IL-6 cell signaling—both associated with lower inflammation and acute phase response—increase schizophrenia risk." (PMID 29094161, 2017). "Interleukin-6 has been widely studied in different aspects of schizophrenia: its onset and progression, association with different clusters of symptoms, response and resistance to the treatment, and metabolical and other comorbid states." (PMID 29163240, 2017). "IL6 -174G>C (rs1800795) G allele was found to be associated with schizophrenia (P = 0.037, OR = 1.41, CI = 1.02–1.96)." (PMID 27177030, 2016). "In IL6, -572 G>C (rs1800796) was found to be associated with schizophrenia at the genotypic level (P = 0.015) with an increased frequency of heterozygous genotype." (PMID 27177030, 2016). "Various lines of evidence suggest a compelling role for IL-6 in the underlying pathogenesis of schizophrenia." (PMID 27206977, 2016). "Associations between a pro-inflammatory state and schizophrenia have been one of the more enduring findings of psychiatry, with various lines of evidence suggesting a compelling role for IL-6 in the underlying pathogenesis of schizophrenia." (PMID 27206977, 2016). "In conclusion, although further studies using a larger cohort of participants are needed, data from the present study suggest that peripheral blood mononuclear cell level of IL-6 mRNA has diagnostic relevancy and predictive value in schizophrenia." (PMID 27206977, 2016). "In Armenian population, an association of rs1800795 (-174G/C) with schizophrenia and corresponding blood level of IL-6 in patients was found to be 1.5-fold higher than in controls." (PMID 27177030, 2016). "With IL-6, a multifunctional cytokine with pro-inflammatory, immunoregulatory, and neuroprotective activities, we report a strong association of IL6-174 G allele and GG genotype and IL6-572 GC genotype with schizophrenia in South Indian population." (PMID 27177030, 2016).
schizophrenia (continued). "A receiver operating characteristics (ROC) curve was generated to examine the diagnostic value of using IL-6 mRNA as a binary classifier (patient with schizophrenia vs. controls)." (PMID 27206977, 2016). "In this study, it was shown that the IL6 -174G/C polymorphism is associated with increased plasma IL-6 in schizophrenia patients and constitutes a risk factor for the disorder." (PMID 25214388, 2015). "We have not confirmed the influence of the IL6 -174G/C polymorphism on IL-6 level in patients with schizophrenia that was shown in one study." (PMID 25214388, 2015). "The comparison of genotype distribution and allele frequency of the IL6 -174G/C polymorphism between schizophrenia patients and healthy controls was presented in our previous paper." (PMID 25214388, 2015). "Both hsCRP and IL-6 levels were associated with insidious psychosis onset, duration of illness and chronic schizophrenia course with deterioration." (PMID 25214388, 2015). "There are also studies reporting the association between the -174 G/C polymorphism in the IL-6 gene (IL6) and schizophrenia." (PMID 25214388, 2015). "Fourth, IL-6 is a key player in established pathogenic models of schizophrenia, including the “ketamine model”." (PMID 25785244, 2015). "We have found that elevated IL-6 level is associated with schizophrenia, that is in line with the results of previous meta-analyses." (PMID 25214388, 2015). "So far, there is one report showing the association between 3′-UTR IL-6 gene polymorphism with the positive symptom dimension in schizophrenia." (PMID 25214388, 2015). "Maternal immune activation and subsequent interleukin-6 (IL-6) induction disrupt normal brain development and predispose the offspring to developing autism and schizophrenia." (PMID 25374324, 2014). "We observed that schizophrenia patients had significantly deficient left and right hippocampal volumes as well as higher plasma IL-6 in comparison with healthy controls." (PMID 24787542, 2014). "In summary, our first time observations suggest significant relationship between GG allele of IL6 promoter polymorphism rs1800795 and reduced hippocampal volume in antipsychotic-naïve schizophrenia patients." (PMID 24787542, 2014). "In this first-time study, we evaluated the relationship between functional polymorphism rs1800795 of IL-6 and hippocampal gray matter volume in antipsychotic-naïve schizophrenia patients in comparison with healthy controls." (PMID 24787542, 2014). "In this study, we evaluated the relationship between IL-6 promoter polymorphism and hippocampal gray matter volume in antipsychotic-naïve schizophrenia patients (N = 28) in comparison with healthy controls (N = 37)." (PMID 24787542, 2014). "In turn, in the study from Armenian population, the IL6 −174G>C [C] allele along with higher IL-6 plasma level were associated with schizophrenia." (PMID 24065520, 2013). "Animal studies suggest that maternal simulated viral or bacterial infection or direct injection with IL-6 during pregnancy can give rise to intermediate phenotypes associated with schizophrenia in adult offspring." (PMID 22188548, 2012). "In conclusion, prenatal influenza virus infection is a plausible environmental risk factor for schizophrenia, acting primarily through maternal immune activation, cytokine dysregulation (especially IL-6), molecular mimicry, epigenetic modifications, and disruption of placental–foetal signalling." (PMID 40806558, 2025). "It has been suggested that genetically determined IL-6 is associated with brain structure and may affect regions involved in developmental neuropsychiatric disorders, including schizophrenia and autism." (PMID 39858450, 2025). "Additionally, a study examining immuno-metabolic profiles identified five cytokines associated with MetS in schizophrenia, including IL-6 and TNF-α35." (PMID 38627438, 2024).
schizophrenia (continued). "This study suggests that genetically determined IL-6 is associated with brain structure and could affect areas involved in developmental neuropsychiatric disorders, such as schizophrenia and autism." (PMID 38673018, 2024). "Our goal was to search for associations between BDNF, CRP, IL-6 and clinical symptoms, cognitive and personal performance in patients with paranoid schizophrenia to try to identify specific subtypes of patients and search for their potential therapeutic targets." (PMID 35873262, 2022). "Thus, according to the paper, an increased level of IL-6 in outpatients with schizophrenia is associated with abnormal thickness of the grey matter in some regions of the cerebral cortex." (PMID 37181835, 2022). "The pathogenic IL-6/IL-23/Th17-axis contributes to the generalized neurocognitive deficit and the phenome of schizophrenia, especially that of DSCZ, due to its key role in peripheral inflammation and neuroinflammation and its consequent immunotoxic effects on neuronal circuits." (PMID 36256663, 2022). "IL-6 was associated with schizophrenia using all three cis instruments." (PMID 34280516, 2021). "One explanation for this divergence could be a potential differential role of IL-6 classic and trans-signalling with regards to schizophrenia risk." (PMID 34280516, 2021). "Also, a recent study indicated that a decrease in Interleukin-6, a pro-inflammatory cytokine, was associated with a decrease in depressive symptoms in first episode schizophrenia patients." (PMID 34702245, 2021). "Moreover, the SIRT1 interacting with IL-6 was significantly responsible for the occurrence of the MetS caused by SGAs in schizophrenia patients." (PMID 33324265, 2020). "However, it is also possible that genetic predisposition for T2DM or schizophrenia influences CRP via mechanisms other than IL-6." (PMID 32828613, 2020). "IL-6 has been shown to have long-term effects on offspring brain development and behavior following maternal immune stimulation and studies suggest that IL-6 is as a key intermediary molecule that predisposes to schizophrenia and autism." (PMID 31071949, 2019). "Moreover, population-based cohort studies have observed that elevated levels of serum CRP and IL-6 in childhood are associated with increased risk of psychotic experience and schizophrenia in adulthood." (PMID 29743584, 2019). "Although one cannot directly compare protein found in the plasma and mRNA cytokine expression levels in cells, it is interesting to note that IL-6 gene expression in blood leukocytes is inversely associated with hippocampal volume in patients with schizophrenia." (PMID 29803226, 2018). "We found that blockade of interleukin-6 effects and low C-reactive protein levels might increase schizophrenia risk, possibly due to increased susceptibility to early life infection." (PMID 29094161, 2017). "The single-nucleotide polymorphism (SNP) G/C at position -174 of the IL-6 gene may also result in increased susceptibility to schizophrenia, although this seems to be highly dependent on environmental factors." (PMID 27206977, 2016). "However, genome-wide linkage analysis has identified the chromosome 7p21.1–22.3 region, which contains the IL6 gene, as one of the susceptibility loci to schizophrenia." (PMID 27177030, 2016). "Interestingly, evidence indicates that IL-6 levels are increased in schizophrenia-risk subjects, with highest levels demonstrated in those who transitioned from risk to acute psychosis." (PMID 27206977, 2016). "A single maternal injection of IL-6 in the middle of corticogenesis causes deficits in prepulse inhibition and lateral inhibition in the offspring, both of which are linked to autism and schizophrenia." (PMID 26074774, 2015). "However, our sample size is similar to that from the only study looking into correlations between the IL6 -174G/C polymorphism and IL-6 level in schizophrenia patients from Armenia." (PMID 25214388, 2015).
schizophrenia (continued). "Third, IL-6 gene polymorphism is associated with schizophrenia [Ref." (PMID 25785244, 2015). "However, the association between plasma IL-6 level and psychopathological manifestation of schizophrenia together with cognitive functioning among this group of patients has not been investigated so far." (PMID 25214388, 2015). "The aim of this study was to assess the influence of serum interleukin-6 (IL-6) level together with the polymorphism in its gene (IL6 -174G/C) and high sensitivity C-reactive protein (hsCRP) levels on clinical manifestation and cognition in schizophrenia patients." (PMID 25214388, 2015). "It has been found that treatment-resistant schizophrenia is associated with elevated level of IL-6." (PMID 25214388, 2015). "However, to the best of our knowledge, the effect of IL-6 promoter polymorphism on hippocampal volume is yet to be evaluated in schizophrenia." (PMID 24787542, 2014). "In relation to IL-6 gene polymorphisms, various lines of evidence support a significant relationship between rs1800795 and pre-term birth - another important obstetric complication that has been associated with elevated risk for schizophrenia." (PMID 24787542, 2014). "In the context of IL-6 gene promoter polymorphism, since GG allele is associated with increased expression of IL-6 gene in the presence of environmental conditions, one would predict this allele to be associated with smaller volume of hippocampus in schizophrenia patients." (PMID 24787542, 2014). "Proinflammatory cytokines especially TNF-α, IL-1ß, and IL-6 exert important roles in mediating acute stress responses and dysregulated production of these cytokines were implicated with chronic CNS inflammation, as well as, schizophrenia." (PMID 22226452, 2012). "Thus, IL-6 modulates the activity of neurotransmitters that are associated with the expression of positive symptoms in schizophrenia and targeted by antipsychotic drugs." (PMID 22911828, 2012). "Furthermore, findings from Mendelian randomization studies suggest that genetically determined elevated peripheral IL-6 levels may causally contribute to the development of both schizophrenia and MDD, with therapeutic potential shown in recent trials." (PMID 39911538, 2025). "Furthermore, IL-6 levels during childhood serve as predictive markers for later schizophrenia risk." (PMID 41303622, 2025). "IL-6 which is found to be highly expressed in psychotic patients is associated with increased oxidative stress and might have a possible association with GABAergic dysfunction in the schizophrenia brain." (PMID 39907868, 2025). "However, the biological mechanisms underlying the sex differences in the association of IL-6 levels with more severe schizophrenia or metabolic aberrations remain unclear." (PMID 37370004, 2023). "It has been suggested that risk factors for schizophrenia, including pre and perinatal infection, childhood adversity, and exposure to infectious agents, might contribute to inflammatory abnormalities then increased IL-6 levels." (PMID 37370004, 2023). "However, what causes the increase in IL-6 levels and what role IL-6 plays in the pathogenesis of schizophrenia remain unclear." (PMID 37370004, 2023). "Therefore, an association between psychosis and a genetic variant that regulates IL-6 activity suggests that the IL-6/IL-6R pathway may be causally related to schizophrenia." (PMID 35963926, 2022). "A recent Mendelian randomization study found that genetically determined IL-6 was associated with changes in brain structure, with stronger associations in the middle temporal gyrus than in the whole brain, potentially involved in neurodevelopmental disorders, including schizophrenia and autism." (PMID 35963926, 2022). "Finally, we aimed to explore the correlations between UA and the cytokines IL-6 and IL-17 and to further test whether altered UA serum levels are associated with specific clinical features of schizophrenia." (PMID 35237183, 2021).
schizophrenia (continued). "Notably, IL-6 is an important cytokine in cerebral function and is associated with schizophrenia." (PMID 30836963, 2019). "A significant inverse relationship was found between CC16 and IL-6 and IL-6R in patients with schizophrenia, but not in normal volunteers, once again pointing to the role of inflammation in schizophrenia, as indicated by higher IL-6 and IL-6R serum level, which may be linked to lower serum CC16." (PMID 30374300, 2018). "Our main hypothesis was that the G allele of the IL6 -174G/C polymorphism could predict the higher expression of IL-6, while the higher IL-6 level could be a risk factor for progressive cognitive decline observed in schizophrenia." (PMID 25214388, 2015). "Notably, IL-6 has been implicated in the pathophysiology of schizophrenia." (PMID 25214388, 2015). "Schizophrenia patients had significantly deficient left and right hippocampal volumes after controlling for the potential confounding effects of age, sex and total brain volume (Table- 2) Also, plasma IL-6 levels were significantly higher in patients than controls." (PMID 24787542, 2014). "Hence, it is possible that maternal immune activation during pregnancy (which is more prevalent in schizophrenia patients compared to healthy controls) might result in hyper-inflammatory IL-6 response in individuals with GG allele." (PMID 24787542, 2014). "The present picture of schizophrenia starts with intrauterine or early postnatal damage to the developing fetal brain by a number of environmental factors, mediated in part by a signaling chain that links cytokine IL-6 and superoxide toxicities in genetically predisposed subjects." (PMID 23750136, 2013). "There is also a positive correlation between sP-selectin and interleukin 6 (IL-6) in patients with schizophrenia." (PMID 40276385, 2025). "Mean values of chlorpromazine equivalent dose (p < .001) and plasma IL-6 levels (p < .001, unadjusted and adjusted for covariates) were significantly lower in the early schizophrenia group than in the established schizophrenia group." (PMID 39911538, 2025). "Chronic low-grade systemic inflammation is frequently observed in patients with schizophrenia, with elevated levels of inflammatory cytokines such as interleukin-6 (IL-6), tumor necrosis factor-alpha (TNF-α), and C-reactive protein (CRP)." (PMID 40786633, 2025). "Elevated IL-6 levels have been consistently observed in the serum and CSF of adults diagnosed with neurodevelopmental disorders such as autism and schizophrenia." (PMID 40276707, 2025). "There is some evidence that elevated peripheral IL-6 levels are related to alterations in brain structure in individuals with schizophrenia." (PMID 39911538, 2025). "Elevated levels of pro-inflammatory cytokines, including interleukin-6 (IL-6) and interleukin-12 (IL-12), have been identified in patients with recent-onset schizophrenia, supporting a psycho-immunological framework for early pathogenesis." (PMID 41302331, 2025). "Future studies that incorporate blood and cerebrospinal fluid measurements from matched individuals will be crucial to validating our findings and providing a more comprehensive understanding of the role of IL-6 in the central nervous system in schizophrenia." (PMID 39911538, 2025). "A subgroup of patients with schizophrenia shows an exaggerated increase in the mRNA levels of inflammatory cytokines, such as IL-1β, IL-6, IL-8 and SERPIN3, in the frontal cortex; these patients are designated high-profile inflammatory patients." (PMID 40276385, 2025). "The inflammatory biomarkers most frequently associated with CT are CRP, IL-1β, IL-6, and TNF-α, parameters which have also been found to be elevated in schizophrenia." (PMID 41049865, 2025). "For example, one recent study found that gray matter volume loss in temporal, hippocampal, and anterior cingulate areas in individuals with established schizophrenia was particularly evident in those who had increased peripheral IL-6 levels." (PMID 39911538, 2025).